TTTY14 (testis expressed transcript, Y-linked 14)
Synonyms: TTY14; NCRNA00137; PRO2834; CYorf14; NCRNA00185
Gene: Long non-coding RNA gene on chromosome Y (18,772,706 to 19,077,555, reverse strand). Ensembl gene ENSG00000176728.
Gene Ontology:
Molecular function: pre-mRNA 5'-splice site binding
Biological process: mRNA 5'-splice site recognition
Cellular component: U1 snRNP
Diseases named in the same sentence as TTTY14 in open-access papers:
TTTY14 is named in the same sentence as 10 diseases in open-access papers, as found by Europe PMC text mining. Sharing a sentence is not in itself a finding about the gene and the disease. The quoted sentences say what the papers report.
epilepsy (1 paper, 2025). A brain disorder characterized by episodes of abnormally increased neuronal discharge resulting in transient episodes of sensory or motor neurological dysfunction, or psychic dysfunction. "RNA-seq analysis of the iPSCs revealed that genes such as TTTY14, TBL1Y, MEG8, MEG9, BCORP1, and RPS4Y1 are not directly related to epilepsy." (PMID 40600194, 2025).
oral squamous cell carcinoma (1 paper, 2020). "TTTY14 has been known to be downregulated in oral squamous cell carcinoma." (PMID 32411183, 2020).
testicular germ cell tumor (1 paper, 2024). A germ cell tumor arising from the testis. "It was observed that the growth of testicular germ cell tumors (TGCT) was notably suppressed in vitro by inhibiting TTTY14 through knockdown." (PMID 39553554, 2024).
testicular tumor (1 paper, 2024). "Nevertheless, these findings indicate that TTTY14 builds up the proliferation of testicular tumor cells, leading to a significant increase in clonogenesis under abnormal conditions, suggesting that cancer cells may acquire greater stemness through TTTY14-mediated proliferation." (PMID 39553554, 2024).
neurological diseases (1 paper, 2025). "Specifically, we chose the genes TTTY14, TBL1Y, MEG8, MEG9, BCORP1, and RPAS4Y1 for analysis, all of which were found to be unrelated to neurological diseases." (PMID 40600194, 2025).
TTTY14 also shares sentences with these, for which no sentence is quoted: cancer (2 papers); adenoma (1); COVID-19 (1); endometriosis (1); tumor (1).